CAST (calpastatin )
Diseases named in the same sentence as CAST in open-access papers (continued):
Sharing a sentence is not in itself a finding about the gene and the disease.
tumor (27 papers, 2001 to 2026). "The analysis of calpastatin immunostaining proved a significant loss of expression in tumor ECs compared to normal vessels." (PMID 39156707, 2024). "We further developed a CAST platform equipped with a PLK1-specific ASO to logically regulate PLK1 gene expression which is highly associated with tumor cell proliferation, to verify CAST effectiveness." (PMID 37580346, 2023). "Six have been indirectly linked to tumour malignancy and are thus new splicing targets to study (CAST, CSF1, PLOD2, SLK, SPAG9, TSC2)." (PMID 33845831, 2021). "High expression of calpastatin was associated with ER positive tumours (χ2=5.720, d.f.=1, P=0.017) and high calpain-1 expression was associated with PgR positive tumours (χ2=5.457, d.f.=1, P=0.019)." (PMID 27323818, 2016). "The calpain system, including the proteolytic enzymes μ-calpain and m-calpain and their endogenous inhibitor calpastatin, has been implicated in cancer progression and response to therapy in a limited number of studies and tumour types." (PMID 22435971, 2012). "The calpain system, including calpastatin, is implicated in tumour progression through its role in multiple cell pathways including cellular migration, apoptosis and cell survival." (PMID 23140395, 2012). "The left tibialis anterior muscle of mice bearing the C26 tumor was transfected with an expression vector encoding a calpastatin species containing, in addition to a single inhibitory unit, also the regulatory L-domain (RNCAST600; transfection efficiency: 30%)." (PMID 28469577, 2017). "In addition to the association with survival of these patients, high calpastatin expression is associated with ER positive tumours and high calpain-1 expression is associated with PgR positive tumours." (PMID 27323818, 2016). "In addition an association between high nuclear calpastatin expression and increased tumour stage (χ2=9.303, d.f.=3, P=0.026) and the presence of vascular invasion (χ2=4.093, d.f.=1, P=0.043)." (PMID 23140395, 2012). "In the bile duct and ampulla carcinoma cohort a significant association was observed between high cytoplasmic calpastatin expression and patients aged above 60 years and high nuclear calpastatin expression and increased tumour stage and the presence of vascular invasion." (PMID 23140395, 2012). "Functional studies revealed that CAST exhibits tumor-promoting activity in both MDA-MB-231 and HCC-1954 cells." (PMID 40175348, 2025). "CAST, a metal ion transition gene, and corresponding proteins such as calpain have been identified as positive factors in tumorigenesis and tumor progression in GC." (PMID 34510798, 2021). "The expression levels of calpain and calpastatin have been described in a number of tumour types, including pancreatic, ovarian and gastro-oesophageal." (PMID 27323818, 2016). "The development of highly specific calpain inhibitors with potential medical applications in cancer should take into account the opposing roles of the calpain/calpastatin system in initial tumor growth and subsequent metastatic dissemination." (PMID 23565252, 2013). "To determine the respective importance of each target, we overexpressed calpastatin in tumor and/or host in isolation." (PMID 23565252, 2013). "Decreased levels of both calpastatin and 130 kDa Ca2+-ATPase have been also detected in the heart of the tumour-bearers." (PMID 11286475, 2001). "Given CAST’s role as a tumor promoter, the elevated CAST levels in TXNIP-OE HCC-1954 cells may counteract TXNIP’s antitumor effects." (PMID 40175348, 2025). "Since CAST exhibited a tumor-promoting function in MDA-MB-231 cells, we investigated whether CAST plays a similar role in HCC-1954 cells." (PMID 40175348, 2025). "Taken together, these results suggest that CAST plays a tumor-promoting role in MDA-MB-231 cells." (PMID 40175348, 2025). "Taken together, these findings further establish CAST’s tumor-promoting activity." (PMID 40175348, 2025).
tumor (continued). "Since CAST has tumor-promoting activity, we hypothesized that CAST upregulation in TXNIP-OE HCC-1954 cells might explain the late-onset acceleration in the growth of TXNIP-OE HCC-1954 tumors in NSG mice." (PMID 40175348, 2025). "Consistent with these in vitro results, CAST-KD MDA-MB-231 tumors in NSG mice exhibited reduced tumor volume and weight relative to WT MDA-MB-231 tumors, whereas CAST-OE MDA-MB-231 tumors displayed greater tumor volume and weight relative to WT MDA-MB-231 tumors." (PMID 40175348, 2025). "Together, these results could also partly explain the tumor-promoting function of CAST, which was upregulated in TXNIP-OE HCC-1954 cells, by counteracting the tumor suppressor activity of TXNIP." (PMID 40175348, 2025). "Moreover, PAAD tumours were insensitive to Erlotinib, Sunitinib and Imatinib in the high mitophagy subtype and high CAST, CCDC6, and ERLIN1 expressed subtypes." (PMID 35938160, 2022). "To further define the mechanisms whereby the calpain/calpastatin system would modify tumor size and metastatic properties, we studied in vitro the influence of calpastatin transgene expression on cell proliferation, spontaneous or induced apoptosis, and migration." (PMID 23565252, 2013). "Main studies report that calpains increase while calpastatin limits tumor dissemination." (PMID 23565252, 2013). "Since IL-17 and Th17 pathway seem to exert anti-tumor properties, it could be hypothesized that immune cells overexpressing calpastatin have reduced ability to limit tumor cell viability and metastatic dissemination." (PMID 23565252, 2013). "The design of our studies allows (i) to specifically inhibit calpain activity using calpastatin and (ii) for the first time, to discriminate the roles of the calpain/calpastatin system in tumor cells (growth, death, migration) and in host (angiogenesis, immune response)." (PMID 23565252, 2013). "Surprisingly, whereas in murine experimental models of cancer, tumor size usually correlates to metastatic dissemination, we observed a discrepancy between the slow tumor growth and the high rate of metastatic dissemination in calpastatin transgenic tumors." (PMID 23565252, 2013). "After tumour transplantation, total calpastatin activity progressively declined, while total calpain activity remained unchanged, resulting in a progressively increasing unbalance in the calpain/calpastatin ratio." (PMID 11286475, 2001). "Additionally, using WGCNA and machine learning, three diagnostic gene signatures (CAST, CCDC6, and ERLIN1) for the high level mitophagy subtype were obtained, which were closely associated with tumour immune microenvironment and chemotherapy sensitivity in PAAD." (PMID 35938160, 2022). "Relative to WT HCC-1954 cells, CAST-OE HCC-1954 cells also demonstrated accelerated tumor growth in NSG mice, as evidenced by greater tumor volumes and weights." (PMID 40175348, 2025). "Consistent with the initial inhibitory events, knocking down CAST in TXNIP-OE HCC-1954 cells led to a significant reduction in cell proliferation, colony formation, and tumor growth in a mouse xenograft model." (PMID 40175348, 2025). "This Cas13a-TAT-crRNA complex (CAST-crRNAa) demonstrated enhanced cellular uptake and reduced PDL1 expression in tumor cells." (PMID 39128990, 2024). "Though CAST has been discovered to have a prominent impact on GC patients’ survival, after multivariate adjustments, multi-database datasets revealed that macrophages might play a key role in immune regulation in the GC microenvironment, promoting tumor suppression." (PMID 35625600, 2022). "Many of the hub AS events, including AS events in KIFB1, SEC31A, CAST and CLSTN1, were up‐regulated in invasive and diffuse GC tissues and were significantly related to extracellular matrix and tumour stromal score." (PMID 32939931, 2020).
tumor (continued). "Furthermore, expression of four proteins is associated with tumor progression/high risk AML: DOT1L, mTOR, VIM and ZNF521, whereas the expression of six proteins is associated with tumor suppression/low risk AML: AEBP2, CAST, CBFB, LSP1, MAP1S and probably PCBP1." (PMID 30634713, 2019). "Compared to wild-type C57BL/6J-Tg(TRAMP)824Ng/J males, TRAMP x CAST/EiJ, TRAMP x NOD/ShiLtJ and TRAMP x NZO/HlLtJ F1 males displayed significant increases in tumor growth." (PMID 23620793, 2013). "It remains unclear whether enhanced calpain kinase activity contributed directly to reduced CAST-KD_TXNIP-OE HCC-1954 cell proliferation and tumor growth." (PMID 40175348, 2025). "Overexpression of CAST, an endogenous inhibitor of calpains, significantly increased xenograft tumor growth for both MDA-MB-231 and HCC-1954 cells, underscoring its novel role as a tumor promoter." (PMID 40175348, 2025). "In human GBM, the transcriptomic data elaborated from the TCGA and GTEx gene expression datasets show that calpain and calpastatin are upregulated in GBM tissues compared to normal brain tissue, likely suggesting a role of the calp/cast system in tumor development and aggressiveness." (PMID 39139809, 2024). "In these three subjects, the negative-mutation status of the tumor for the specific mutation detected in the NLP was confirmed using highly sensitive and specific TaqMan PCR (CAST-PCR)." (PMID 34257550, 2021). "When administered intravesically, the interaction with FCS facilitates transepithelial delivery of CAST-crRNAa, rearranging tight junction proteins in bladder epithelium and enabling TAT-mediated cellular internalization and PDL1 expression regulation in tumor tissues." (PMID 39128990, 2024). "Furthermore, the mRNA expression of CAST, CCDC6 and ERLIN1 could potentially predict the tumour’s sensitivity to Erlotinib, Sunitinib and Imatinib." (PMID 35938160, 2022).
cancer (22 papers, 2012 to 2025). A tumor composed of atypical neoplastic, often pleomorphic cells that invade other tissues. "Altered regulation of the calpastatin-calpain proteolytic system is associated with several pathological disorders, including cancer." (PMID 29581866, 2018). "Further research into the interactions between TXNIP, CAST, and IL-24 is essential to better understand their roles in cancer." (PMID 40175348, 2025). "Lastly, the complex roles of CAST and IL-24 in cancer underscore the need for more comprehensive studies to fully understand the diverse effects and therapeutic potential of these molecules." (PMID 40175348, 2025). "CAST is an endogenous inhibitor of calpains (m-calpain and μ-calpain) but its involvement in cancer biology remains poorly understood." (PMID 40175348, 2025). "The calpain/calpastatin (calp/cast) proteolytic system is involved in critical physiological processes and cancer progression." (PMID 39139809, 2024). "CAST expression and pan-cancer surveyance were analyzed using the Human Protein Atlas (HPA) and Gene Expression Profiling Interactive Analysis 2 (GEPIA2) database." (PMID 35625600, 2022). "Calpastatin levels, however, vary across cancer types as the protein is reported to have high expression in endometrial cancer and low expression in rhabdomyosarcoma." (PMID 29581866, 2018). "While calpain‐1 and calpastatin levels varied widely in the cancer cell lines we examined in this study, calpain‐2 levels were consistently detected and showed interesting patterns of low, moderate, and high expression." (PMID 29210197, 2018). "We also showed that casein kinase 2, a pro-survival kinase overexpressed in many cancer types, phosphorylated calpastatin at Ser-633." (PMID 29581866, 2018). "Overall, our results evidence that studies of the calpain/calpastatin in cancer models should distinguish the role of calpains in tumoral cells and in host tissues/immune system." (PMID 23565252, 2013). "However, future studies are needed to determine if calpastatin contributes to radiation resistance in other cancers as well." (PMID 29581866, 2018). "However, the exact role of CAST related to cancer susceptibility or DNA repair has not been elucidated yet." (PMID 23593158, 2013). "Calpastatin (CAST) is involved in many important physiological processes, including cell cycle, ECM, cancer cell proliferation, metastasis, and apoptosis." (PMID 35265613, 2022). "(A) Kaplan-Meier plot of the survival of male mice in which cancer was observed during gross necropsy (N = 38 male mice; WT Sham 5, L-RKO Sham 9, WT CAST 10, L-RKO CAST 14)." (PMID 32720643, 2020). "The highest up-regulated lncRNA was lnc-MMP10-3 (absolute FC = 1469.95) among ESCC tissues versus paired non-carcinoma tissues and a total of 809 genes (e.g. S100A16, OLFML2B, and CAST) were related to lnc-MMP10-3 as the standard of absolute PCCs value > 0.8." (PMID 31235759, 2019). "Despite a clear involvement of the calpastatin-calpain system in cancer, its contribution to treatment resistance has not yet been explored." (PMID 29581866, 2018). "Our results indicate that calpastatin phosphorylation promotes radiation resistance in GBM cells by increasing the activity of calpain proteases, which are known to promote survival and invasion in cancer." (PMID 29581866, 2018). "The lack of effect of RNCAST600 in preventing cancer-induced muscle wasting could depend on a sort of “calpastatin resistance”." (PMID 28469577, 2017). "Future challenges will be to explore whether the transfection of different forms of calpastatin (i.e., without L-domain or with an L-domain lacking exon 6) could affect cancer-induced muscle wasting." (PMID 28469577, 2017).
infection (18 papers, 2008 to 2025). The state of being infected such as from the introduction of a foreign agent such as serum, vaccine, antigenic substance or organism. "Infection of the CAST and PWK mice led to rapid weight loss which was more profound and longer lasting for CAST." (PMID 39149485, 2024). "Recent studies have shown that infection of host cells with Mycoplasma hyorhinis caused inhibition of calpain activity through upregulation of its inhibitor, calpastatin." (PMID 21507248, 2011). "In contrast, PWK mice, which lost significant weight and displayed some susceptibility to the infection, had statistically significant (p < 0.0001) reduced levels of the virus in the lungs (2.84 ± 0.19 log10PFU, day 3 post-infection) compared to K18-hACE2 and CAST mice." (PMID 39149485, 2024). "This is supported by studies in CAST/EiJ mice, which showed that infection with clade IIb triggered a faster and more robust immune response than clade IIa, resulting in less severe disease." (PMID 41476947, 2025). "Ultimately, all female and nearly all male CAST mice succumbed to infection with Beta VOC by either 5- or 7-days post infection for females and males, respectively." (PMID 39149485, 2024). "The cytokine signatures of CAST and K18-hACE2 mice show sustained increases at 3- and 5- days post-infection for a number of known pro-inflammatory chemokines and cytokines." (PMID 39149485, 2024). "CAST mice displayed the highest levels of bronchiolar necrosis throughout all 5 days of infection analyzed." (PMID 39149485, 2024). "TNF-α promoted the proliferation, migration, and tube formation in HUVECs, but these effects were attenuated by infection with Ad-CAST." (PMID 32665543, 2020). "We showed that TNF-α induced β-catenin and suppressed IκB expression in HUVECs, and these effects were both attenuated by infection with Ad-CAST." (PMID 32665543, 2020). "For example, highly susceptible strains (C57BL/6J, 129S1/SvlmJ, CAST/EiJ) exhibited a strong increase in IFIT3 and IFIT44 expression after infection but only a relatively low increase in expression was observed in the resistant strain PWK/PhJ." (PMID 27193691, 2016). "In summary, CAST/EiJ mice exhibited in general much lower numbers of immune cells in the lungs before and after infection." (PMID 26921172, 2016). "In summary, the amount of granulocytes in the blood of CAST/EiJ mice increased after infection which suggests a normal primary signaling of infected cells to the hematopoietic system and the release of leukocytes into the blood." (PMID 26921172, 2016). "DCQ analysis of the lung transcriptome showed equal numbers of monocytes and macrophages in CAST/EiJ and 129S1/SvlmJ mice and a much stronger reduction in dendritic cells in CAST/EiJ compared to 129S1/SvlmJ mice after infection." (PMID 26921172, 2016). "To investigate the role of calpain in ROS production, we over-expressed calpastatin in HUVECs by infection with Ad-CAST and then incubated these cells with normal (5 mmol/L) or high glucose (30 mmol/L) for 48 hours." (PMID 24886224, 2014). "Another example was the Tdrd3 gene, which showed differential isoform expression in CAST/EiJ mice on day 2 after MA15 infection." (PMID 24902603, 2014). "Control cells and calpastatin- or calpain-overexpressing NIH-3T3 cells (infection efficiencies were >95%) were stimulated with LPS or IL-17, and the IL-6 concentration in the culture supernatants was measured by ELISA." (PMID 22046434, 2011). "Remarkably, infection of old VSMC with an adenovirus harboring CAST indeed inhibits calpain-1 activity and generates a pattern of proteolytic products of vimentin resembling that from the untreated young cells (30 mo)." (PMID 18493299, 2008). "Since CAST mice display several similarities to human infection, they could potentially serve as a better model for evaluation of next generation therapeutics and vaccines against SARS-CoV-2." (PMID 39149485, 2024).